IL10 (interleukin 10)
Diseases named in the same sentence as IL10 in open-access papers (continued):
Sharing a sentence is not in itself a finding about the gene and the disease.
Hyperglycemia (86 papers, 2005 to 2026). An increased concentration of glucose in the blood. "Hyperglycemia caused a decrease in interleukin 6 (Il-6) and an increase in tumor necrosis factor alpha (Tnf-α), Il-10, F4/80, tumor growth factor beta (Tgf-β), and insulin-like growth factor 1 (Igf-1)." (PMID 36722656, 2023). "Hyperglycemia due to gestational diabetes has been associated with lower plasma serotonin and IL-10 levels." (PMID 38138954, 2023). "In our patients, stress hyperglycemia was also found to be independently associated with higher levels of IL-10 and by its ratio to TNF-α." (PMID 36059840, 2022). "While the exact mechanisms are still unclear, evidence points in either a pro-inflammatory effect of high IL-10 levels causing T-cell exhaustion and/or an IL-10 “resistance” which is entangled with hyperglycemia." (PMID 36275812, 2022). "IL-10 deficiency during lipopolysaccharide-induced inflammation and hyperglycemia promotes reduced endothelium-dependent relaxation to acetylcholine in carotid arteries, showing that IL-10 protects the endothelial function." (PMID 28466012, 2017). "Our results indicate that the normal anti-inflammatory actions of IL10 are impaired in T2D, effects that appear to be linked to hyperglycemia." (PMID 26883847, 2016). "Patients with hyperglycemia on admission to the ICU had increased levels of IL-6 and IL-10, although after multivariate analysis only IL-6 was associated with hyperglycemia." (PMID 16356228, 2005). "Maternal hyperglycemia associated with urinary incontinence creates an inflammatory environment, characterized by reduced melatonin and IL-10 and increased IL-1β, IL-8, and TNF-α in the plasma of mothers with gestational diabetes mellitus and incontinence-specific urinary tract issues." (PMID 41295285, 2025). "Possibly, the found association between admission glucose and IL-10 could be explained as a counter-regulatory response to insulin resistance and stress hyperglycemia due to acute illness." (PMID 39962379, 2025). "Longer aortic cross-clamp times may increase inflammatory mediators (e.g., IL-6, IL-8, and IL-10), which can predispose patients to hyperglycemia." (PMID 40260105, 2025). "There is significant concern that current corticosteroid dosing may result in inadequate modulation of IL-6 and IL-10 levels and subsequent treatment failure or in toxicity from steroid-induced hyperglycemia or infection risk." (PMID 37484782, 2023). "Besides, high serum HbA1c expression in patients with T2DM may cause a decrease of IL-10, therefore high IL-10 grade may be related to hyperglycemia." (PMID 36438735, 2022). "Concomitantly, NGF triggers an anti-inflammatory response in surface inducing production of IL-1 receptor antagonist and IL-10 and dampens NF-κB activation, thereby reducing hyperglycemia-driven corneal inflammation." (PMID 41471293, 2025). "In experimental diabetic models, transferring IL-10-producing Bregs delays hyperglycemia onset and reduces pancreatic islet inflammation, underscoring IL-10’s protective role." (PMID 40370441, 2025). "The results showed that in rats with hyperglycemia, the concentrations of pro-inflammatory factors NF-κB p-p65 and IL-1β increased significantly, whereas the anti-inflammatory factor IL-10 decreased significantly." (PMID 41463431, 2025). "hAC and chondrosarcoma cell lines used in IL-10-stimulated cell culture demonstrated reduced proliferation ability in hyperglycaemia and hyperinsulinaemia compared with normal glycaemic conditions." (PMID 38606593, 2024). "Owing to impaired innate immunity, hyperglycaemia, and oxidative stress together induce elevation in the level of pulmonary cytokines such as interleukin (IL)-17 A, IL-8, and IL-10, which leads to increased pro-inflammatory responses." (PMID 37370020, 2023). "FGF-21 increased during both hypoglycemia and hyperglycemia while IL-6 and IL-10 increased during hypoglycemia." (PMID 37400734, 2023).
Hyperglycemia (continued). "PBA notably diminished hyperglycemia-enhanced expression of TNF-α and IL-6, and elevated hyperglycemia-reduced expression of IL-10 at 0 and 6 h after reperfusion." (PMID 35289326, 2022). "Transfection of Gm10451 siRNA into MIN6 cells increased IL-10 secretion and decreased IL-1 secretion, with statistically significant differences in contrast to the hyperglycemia group (sh-NC group) (p < 0.05)." (PMID 36003336, 2022). "Gm10451 lentivirus transfection into MIN6 cells reduced the secretion of IL-10 and increased the secretion of IL-1, with statistically significant difference when compared with the hyperglycemia group (ON-NC group) (p < 0.05)." (PMID 36003336, 2022). "A similar resistance to IL-10’s anti-inflammatory action was observed in macrophages cultured in high-glucose media suggesting that hyperglycemia was responsible for the reduced anti-inflammatory function of IL-10 in T2D." (PMID 34234779, 2021). "Other cytokines and factors, such as TGF-β, PDGF, CTGF, IL-10, high glucose (hyperglycemia), and reactive oxygen species (ROS) are also known for stromal transformation." (PMID 34885065, 2021). "In our study, both doses of extract and quercetin increased significantly the IL-10 levels, thus demonstrating the protective effect against inflammation in HUVECs exposed to hyperglycemia." (PMID 32824505, 2020). "Hyperglycemia reduces the secretion of IL-10 by inducing the reduction of Arg1 and Mrc1 expression and the activation of the STAT3 and STAT6 signaling pathways to inhibit M2-like KC polarization." (PMID 32676077, 2020). "More importantly, inhibition of CHOP over-activation in hyperglycemia KCs post-IR restored anti-inflammatory IL-10 production." (PMID 29081777, 2017). "Our findings indicate that exposure to high glucose can also reduce the capacity of macrophages to respond to IL10, linking hyperglycemia in T2D to IL10 hyporesponsiveness." (PMID 26883847, 2016). "In this study we provide evidence from both human and cell culture studies that T2D in vivo and hyperglycemia in vitro are related to a reduced anti-inflammatory function of IL10." (PMID 26883847, 2016). "The present findings indicate that IL10 hyporesponsiveness or “IL10 resistance” occurs in immune cells from humans with T2D and in macrophages cultured in physiologically-relevant hyperglycemia." (PMID 26883847, 2016). "The purpose of this study was to determine how T2D and hyperglycemia influenced the anti-inflammatory abilities of IL10 in immune cells." (PMID 26883847, 2016). "We aimed to study how IL10 functioned to inhibit inflammation in immune cells in the context of T2D and hyperglycemia." (PMID 26883847, 2016). "In addition, the concentrations of serum NF-κB p-p65, IL-1β, and IL-10 in all animals were measured by ELISA to further evaluate the expression of inflammatory factors in chickens and rats with hyperglycemia induced by STZ." (PMID 41463431, 2025). "In stratified analyses, in non-diabetic AMI patients stress hyperglycemia at admission was independently associated with the cytokines IL-6, IL-8, IL-10, CCL20, and MCP-1." (PMID 39962379, 2025). "In contrast, synthesis of proteoglycan in OA hAC was lowered in hyperglycaemia with IL-10." (PMID 38606593, 2024). "In general, treatments with D3T under hyperglycemia showed a greater induction in the relative expression of IL-10 compared to that treated with RSV, suggesting that regulation under Nrf2 stimulation could be more efficient than mTOR induction." (PMID 37630249, 2023). "However in T2D, hyperglycemia induces islet macrophages to become less responsive to IL-10 signaling and to maintain a more pro-inflammatory M1-like state." (PMID 35145521, 2022). "Moreover, both doses of Physalis fruits extract decreased IL-6 levels and increased IL-10 in hyperglycemia in parallel with a reduction of caspase-3." (PMID 32824505, 2020).
Hyperglycemia (continued). "Therefore, the hyperglycemia-induced overexpression of C/EBP homologous protein (CHOP) inhibits the polarization of M2-like KCs secreted IL-10, leading to inflammatory activation of KC during liver I/R." (PMID 32676077, 2020). "Hence, the effects of IL-10 under hyperglycemia (HG) and hyperinsulinemia (HI) in human articular chondrocytes (hAC) and chondrosarcoma cell line Okayama University Medical School (OUMS)-27 were examined." (PMID 30759730, 2019). "However, so far, little information about the role of IL-10 and its mechanism of action in healthy and in OA cartilage under the conditions of hyperglycemia (HG) is available." (PMID 30759730, 2019). "Even in the absence of concurrent infection, hyperglycemia is associated with a systemic inflammatory state characterized by elevated ratios of diverse pro-inflammatory cytokines to IL-10 in plasma." (PMID 31271354, 2019). "Thus, hyperglycemia-induced CHOP over-activation inhibits IL-10-secreting M2-like macrophage polarization by liver-resident macrophages, thereby leading to excessive inflammation and the exacerbation of liver IR injury in diabetic/hyperglycemic hosts." (PMID 29081777, 2017). "Interestingly, we found that hyperglycemia inhibited IL-10-secreting M2-like macrophage polarization, as revealed by decreased Arg1 and Mrc1 gene induction accompanied by a decrease in STAT3 and STAT6 signaling pathway activation." (PMID 29081777, 2017). "Indeed, we also noted elevated levels of IL-10 in response to IR injury and hyperglycaemia." (PMID 40240715, 2025). "For instance, transient hyperglycemia can induce adaptive responses such as increased production of antioxidants (e.g., glutathione) or upregulation of anti-inflammatory cytokines like IL-10, which may temporarily suppress pro-inflammatory mediators like IL-6 and IL-8." (PMID 41126323, 2025). "The evidence showed hyperglycemia to be associated with unfavorable treatment outcomes; altered counts and functioning of dendritic cells, monocytes, and CD4+ T cells; and changes in cytokine levels (mainly INF-γ, IL-17, IL-1β, IL-2, IL-6, IL-10, and TNF-α) in patients with DM-TB." (PMID 39981106, 2024). "Moreover, it has been suggested that hyperglycemia may decrease cytokine production, such as IL-2, IL-6, and IL-10, impair leukocyte function, and impair leukocyte defense against infection." (PMID 39744260, 2024). "In addition, hyperglycemia activated NFkB, maintained low levels of IL-10 and induced apoptosis." (PMID 32824505, 2020). "Although increased levels of TGF-β1 may be induced by metabolic abnormalities like hyperinsulinemia and hyperglycemia are implicated in the development of cardiomyopathy, the reason for increased levels of IL-10 in our study is not known." (PMID 23843977, 2013). "In this analysis, levels of IL-10, IL-10/TNF-α ratio, and CXCL10 were found to be independent predictors of stress hyperglycemia as defined by a SHR of more than 1.14." (PMID 36059840, 2022). "Older age, neutrophilia, thrombocytopenia, hyperglycemia and elevated LDH, serum creatinine, BUN, hs-cTnT, BNP, PCT, hsCRP, IL-6, IL-10, TNFα and poorly controlled hyperglycemia were also associated with death." (PMID 33382747, 2020). "Hyperglycemia-induced CHOP over-activation inhibited M2 polarization and suppressed IL-10 production, which is responsible for the hyper-inflammatory immune response and exacerbated liver IR injury observed in diabetic/hyperglycemic hosts." (PMID 29081777, 2017). "In order to determine if hyperglycemia, the primary pathophysiological hallmark of T2D, might be responsible for reducing the anti-inflammatory function of IL10, we cultured RAW264.7 mouse macrophages in normal (5 mM) and high (15 mM) glucose and treated the cells with LPS +/− IL10." (PMID 26883847, 2016). "Our findings in cultured macrophages show that hyperglycemia impacts IL10 signaling at the level of STAT3, a key node in intracellular IL10 signal transduction." (PMID 26883847, 2016).
Hyperglycemia (continued). "In contrast, in chickens, STZ-induced hyperglycemia led to non-significant upward trends in NF-κB p-p65 and IL-1β concentrations as well as a non-significant downward trend in IL-10." (PMID 41463431, 2025). "In streptozotocin-induced T1D in wild-type mice, Schistosoma mansoni infection inhibits the breakdown of pancreatic islets and hyperglycemia through increased Arg-1 and Ym1 expression rather than through processes that rely on Treg, IL-4, IL-13, and IL-10." (PMID 40299229, 2025). "The byproducts of hyperglycaemia, AGEs, regulate inflammation by increasing NF-κB nuclear localisation and induction of IL-1β, TNF-α, macrophage inflammatory protein 2 (MIP2), IL-6 and IL-10." (PMID 37670018, 2023). "Although most participants did not have baseline HbA1c levels indicative of overt DM, and most had resolution of hyperglycemia, those with increased HbA1c levels tended to display a more pro-inflammatory state characterized by elevated CD62 P-selectin and depressed IL-10 plasma levels." (PMID 37313404, 2023). "Patients with stress hyperglycemia had significantly higher levels of IL-10, IL-10/TNF-α ratio, CXCL10, and CRP than patients without stress hyperglycemia." (PMID 36059840, 2022). "Log IL-10, IL-10/TNF-α ratio, and log CXCL10, but not log IFN-γ were independently associated with stress hyperglycemia." (PMID 36059840, 2022). "Thus, considering the defect in granuloma formation as one the main containment mechanisms of transmission and severity of the disease, our data add evidence in an ex vivo assay about the lower production of IL-10 in patients living with DM2 and hyperglycemia." (PMID 34084753, 2021). "Hyperglycemia promoted an increase in the levels of IL-10 in comparison with those in nonhyperglycemic animals." (PMID 32841254, 2020). "However, other studies indicate that IL10 hyporesponsiveness or “IL10 resistance” occurs in immune cells from humans with T2DM and in macrophages cultured in physiologically-relevant hyperglycemia." (PMID 31554278, 2019). "To test this hypothesis, we quantified the gene expression of macrophage-secreted cytokines (IL-1β, IL-6, TNF-α, IL-10) and chemokines (CCL2) in the lacrimal gland, conjunctiva and cornea of non-diabetic normoglycemic mice and diabetic mice with 7, 14, and 28 days of hyperglycemia." (PMID 39749321, 2024). "Hyperglycemia is closely related to the excess generation of reactive oxygen species (ROS) and oxidative stress which can up-regulate the levels of inflammatory factors including tumor necrosis factor-alpha (TNF-α), interleukin-6 (IL-6) and reduces the level of interleukin 10 (IL-10)." (PMID 37396948, 2023). "This hyperglycemia-induced potentiation of SARS-CoV-2 replication in monocytes requires glycolytic flux, which is noteworthy (and perhaps further supportive of IL-10 resistance) because the anti-inflammatory effects of IL-10 in macrophages are typically mediated by oxidative metabolism." (PMID 34234779, 2021). "Hyperglycemia promoted increased IL-10 levels compared to non-hyperglycemic ones." (PMID 32841254, 2020). "Thus, similar to humans with T2D, hyporesponsiveness to IL10 as a result of hyperglycemia in cultured macrophages did not appear to be explained by reduced protein levels of the IL10 receptor or downstream signalling proteins." (PMID 26883847, 2016). "The hyporesponsiveness to IL10 in the presence of high glucose appears linked to reduced intracellular signal transduction through STAT3, whereas the anti-inflammatory actions of AQX-MN100, a small molecule activator of SHIP1, is not affected by hyperglycemia." (PMID 26883847, 2016). "Chronic hyperglycemia modulates immune responses and triggers inflammation through the activation of Toll-like receptors (TLRs), leading to an increase in the proinflammatory cytokines, IL1, IL6, TNFα and interferon γ(IFNγ), and a decrease in the levels of interleukin 10 (IL10)." (PMID 24260283, 2013).
Hyperglycemia (continued). "Under these conditions, all five recipient mice developed hyperglycemia within 4 weeks after co-infusion of diabetogenic cells (data not shown), indicating that IL-10 secreted by DNCD3 differentiating splenocytes played a critical role to their anti-diabetogenic effect." (PMID 20625402, 2010). "Notably, the DIO model does not develop hyperglycemia, which may in part be due to the IL-10 expressing islet lymphocytes." (PMID 35145521, 2022).